BRAF (B-Raf proto-oncogene, serine/threonine kinase)
Diseases named in the same sentence as BRAF in open-access papers (continued):
Sharing a sentence is not in itself a finding about the gene and the disease.
interstitial lung disease (4 papers, 2017 to 2024). A diverse group of lung diseases that affect the lung parenchyma. "Of note, the expression of driver mutations in EGFR, BRAF, and KRAS G12C in patients with NSCLC with concurrent interstitial lung disease is vastly different compared to those patients with NSCLC without Interstitial Lung Disease." (PMID 39062713, 2024).
interstitial nephritis (4 papers, 2017 to 2024). Inflammation of the renal tubules and supporting tissues of the kidney. "A few cases of tubulointerstitial nephritis and one case of nephrotic syndrome have been reported after treatment with BRAF/MEK inhibitors dabrafenib and trametinib." (PMID 39677216, 2024). "Most of these are related to the use of BRAF inhibitors and involve interstitial nephritis with acute tubular necrosis." (PMID 28640105, 2017).
Langerhans cell sarcoma (4 papers, 2014 to 2020). A neoplastic proliferation of Langerhans cells with overtly malignant cytologic features. "These exceptions were: the presence of BRAF mutations in all solitary skin LCHs and a somewhat lower rate of BRAF mutations in Langerhans cell sarcomas (17%)." (PMID 24938183, 2014). "In addition, the comforting effect of BRAF inhibitor was also observed in the treatment of Langerhans cell sarcoma and histiosarcoma with the BRAF V600E mutation." (PMID 32476297, 2020). "First, our BRAF mutated Langerhans cell sarcoma patient had died; therefore, given the rarity and aggressiveness of this disease the potential of targeting BRAF mutations should not be ignored." (PMID 24938183, 2014).
lymphopenia (4 papers, 2015 to 2025). Reduction in the number of lymphocytes. "Regarding lymphocyte subsets, CD4+ lymphopenia was observed in 34.5% of patients with BRAF mutations, whereas only 9.1% of MAP2K1-mutated individuals exhibited this finding." (PMID 40692796, 2025). "The patients with lymphopenia included a higher percentage of individuals with M1d at baseline (42.9% versus 28.4%, p = 0.117), as well as a higher percentage of BRAF mutation (51.0% versus 32.8%, p = 0.057)." (PMID 35805052, 2022). "Similarly, CD8+ lymphopenia was more frequent in BRAF-mutated patients (31.0%) compared to MAP2K1 (9.1%)." (PMID 40692796, 2025). "Similarly, lymphocytosis was more common in the MAP2K1 cohort (16.7%) compared to BRAF (3.1%), while lymphopenia was higher in BRAF-mutated patients (25.0%) than in MAP2K1-mutated patients (8.3%)." (PMID 40692796, 2025). "Our findings demonstrate a significant lymphopenia in patients treated with the BRAF inhibitor vemurafenib, which is further augmented by dexamethasone and predisposes to infection." (PMID 25897843, 2015). "This could be associated with an increased infection rate independent of BRAF inhibitor treatment or lymphopenia." (PMID 25897843, 2015).
mucoepidermoid carcinoma (4 papers, 2019 to 2026). A carcinoma morphologically characterized the presence of cuboidal mucous cells, goblet-like mucous cells, squamoid cells, cystic changes, and a fibrotic stromal formation. "Thus, BRAF inhibitors may prove to be a useful targeted medical therapy in the treatment of a subset of patients with aggressive sclerosing mucoepidermoid carcinoma with eosinophilia tumors who exhibit BRAF activating mutation." (PMID 31882020, 2019). "RET/PTC rearrangements were found in combined PTC and mucoepidermoid carcinoma, whereas no BRAF or RAS mutations were detected in mucoepidermoid carcinomas." (PMID 32632840, 2020).
myocardial infarction (4 papers, 2016 to 2022). Gross necrosis of the myocardium, as a result of interruption of the blood supply to the area, as in coronary thrombosis. "Meta-analysis comparing combination therapy versus BRAF inhibitor monotherapy concluded that the risk ratio of myocardial infarction was similar in both groups." (PMID 35492830, 2022). "The incidence of myocardial infarction in the coBRIM trial was 0.4%55 in the BRAF inhibitor/MEK inhibitor group versus 0% in the BRAF inhibitor plus placebo group." (PMID 35492830, 2022).
neutropenia (4 papers, 2018 to 2025). A decrease in the number of neutrophils found in the blood. "These agents have been proposed as relatively safe drugs, even in pretreated patients, with severe neutropenia and (in the case of BRAF inhibitors) infections." (PMID 34202156, 2021).
nodular goiter (4 papers, 2012 to 2024). Goiter characterized by discrete tissue mass(es) that may or may not produce thyroid hormones. "Histological work up revealed a unifocal papillary microcarcinoma (9 mm, pT1a, R0), positively tested for the BRAF V600E mutation, embedded into the hyperfunctional nodular goiter." (PMID 23657056, 2013).
oral squamous cell carcinoma (4 papers, 2012 to 2024). "Together with a previous study that reported a BRAF mutation frequency of 2.4% (1/42) in oral squamous cell carcinoma, our results suggest that the BRAF mutation frequency is much lower in HNSCC than in other cancers." (PMID 22994622, 2012).
Pancytopenia (4 papers, 2015 to 2026). An abnormal reduction in numbers of all blood cell types (red blood cells, white blood cells, and platelets). "There is only one other case of relapsed BRAF V600E-mutated HCL presenting with pancytopenia and CNS involvement, initially thought to be mantle cells." (PMID 36713531, 2022). "100% of patients had pancytopenia at diagnosis.9% of patients had mutation of BRAF V600E." (PMID 26261698, 2015).
panniculitis (4 papers, 2015 to 2025). Inflammation of the subcutaneous adipose tissue. "So far, only one retrospective analysis showed a possible correlation between the cutaneous side effects panniculitis and vitiligo-like lesions and the treatment outcome upon the BRAF plus MEK inhibitor combination dabrafenib and trametinib." (PMID 34109122, 2021). "The immune related skin lesions, panniculitis and vitiligo, occurring during treatment with BRAF and MEK inhibitors, are easily detectable and contribute to identify a patient subset destined to obtain a long-term clinical benefit from the therapy." (PMID 30939167, 2019).
paraganglioma (4 papers, 2017 to 2022). A benign or malignant neoplasm arising from paraganglia located along the sympathetic or parasympathetic nerves. "Fusion genes involving MAML3 (5%), BRAF (0.6%), NGFR (0.6%), and NF1 (0.6%) have been described as genetic disease drivers in a subset of paragangliomas." (PMID 32926213, 2020).
peritoneal carcinoma (4 papers, 2020 to 2026). A peritoneum cancer that is located in the inside of the abdomen. "It takes into account peritoneal cancer index, nodal status, differentiation grading, and KRAS/BRAF mutations and allows categorization of patients into 4 survival groups with a prediction performance of 0.70 (development/validation area under the curve)." (PMID 36077810, 2022). "Nonetheless, in our cohort, these data on the peritoneal carcinoma index were not available to determine those patients with the BRAF V600E mutation who are most likely to benefit from resection of peritoneal carcinomatosis, as has previously been confirmed the prognostic value of OS." (PMID 34572480, 2021). "Variables included peritoneal cancer index (PCI), tumor location, histology, HIPEC regimen, and KRAS/BRAF/SMAD4 status." (PMID 41595218, 2026).
retinoblastoma (4 papers, 2018 to 2025). A malignant tumor that originates in the nuclear layer of the retina. "The relationship between BRAF mutations and RB in retinoblastoma is not as well documented as other genetic alterations like RB1 mutations or MYCN amplification." (PMID 40317918, 2025). "Though uncommon in retinoblastoma, the presence of both RB1 and BRAF mutations could theoretically result in a more aggressive tumor phenotype." (PMID 40317918, 2025). "Notably, the coexistence of BRAF and RB1 mutations in RB‐68 may have resulted in stage E retinoblastoma and the patient underwent enucleation." (PMID 40317918, 2025). "Research continues to explore the complex genetic landscape of cancers, and while BRAF mutations are not a primary driver in retinoblastoma, understanding their role in secondary malignancies could be significant for comprehensive patient care." (PMID 40317918, 2025). "Treatment with BRAF inhibitors was initiated for LCH, followed by chemotherapy and left eye enucleation for retinoblastoma." (PMID 41427451, 2025). "The other retinoblastoma had multiple genomic abnormalities on chromosomes 6, 7, and 8, in line with chromothripsis, chromoanasynthesis or chromoplexy including an amplification containing the downstream MYC(N) signaling component, BRAF." (PMID 39079981, 2024).
rheumatoid arthritis (4 papers, 2010 to 2023). A chronic, systemic autoimmune disorder characterized by inflammation in the synovial membranes and articular surfaces. "Autoantibodies to the catalytic domain of v-raf murine sarcoma viral oncogene homologue B1 (BRAF) have been recently identified as a new family of autoantibodies involved in rheumatoid arthritis (RA)." (PMID 22174938, 2011). "According to the results of molecular docking, in the context of rheumatoid arthritis, phytocannabinoids may bind to important target proteins such as PIK3CA, AKT1, MAPK9, PRKCD, BRAF, IGF1R, and NOS3." (PMID 36983855, 2023).
skin toxicity (4 papers, 2016 to 2025). "Skin toxicity is also common with BRAF inhibitors, which led to treatment discontinuation among patients who received vemurafenib in a study." (PMID 41035796, 2025). "In conclusion, first-line panitumumab + FOLFIRI was associated with consistently favourable efficacy in patients with RAS WT/BRAF WT vs MT mCRC tumours and was well tolerated, despite the expected high incidence of skin toxicity." (PMID 27764839, 2016).
small cell carcinoma (4 papers, 2021 to 2023). A neuroendocrine carcinoma composed of small malignant cells which are often said to resemble "oat cells" under the microscope. "Other mechanisms include small cell carcinoma transformation, gene amplification of EGFR, ERBB2, and MET and additional mutations in PI3K, BRAF, and KRAS32–36." (PMID 33863951, 2021).
systemic lupus erythematosus (4 papers, 2011 to 2023). An autoimmune multi-organ disease typically associated with vasculopathy and autoantibody production. "Among the tested antigens, dsD4, which contains the sequence of the human oncogene BRAF, showed a particularly strong presence in localized scleroderma but not systemic lupus erythematosus." (PMID 38139335, 2023).
testicular germ cell tumor (4 papers, 2018 to 2025). A germ cell tumor arising from the testis. "Moreover, when examining germ cell tumors, it is noteworthy that activating BRAF missense mutations were identified in 9% of nonseminomas, but were notably absent in seminomas." (PMID 40002790, 2025).
tubulovillous adenoma (4 papers, 2007 to 2021). An epithelial neoplasm morphologically characterized by the presence of a villous and a tubular architectural pattern. "K-ras mutation was frequently detected in tubulovillous adenomas (24 out of 40, 60%), while BRAF mutation was mostly observed in serrated adenomas (5 out of 8, 63%)." (PMID 17923875, 2007).
Ulceration (4 papers, 2017 to 2025). "Ulceration was recognized in 343 patients (61.6%) and positive BRAF status in 278 patients (49.9%)." (PMID 37345002, 2023). "Ulceration and BRAF status correlated to the number of iNOS+ and arginase+ cells." (PMID 32843682, 2020). "Regarding data limitations, the datasets used lacked key information including BRAF/NRAS gene mutation status and contained insufficient ulcer samples, affecting the comprehensiveness of the analysis." (PMID 40547036, 2025).
vulvar melanoma (4 papers, 2014 to 2022). A usually pigmented, nodular or polypoid malignant neoplasm that originates from melanocytes and arises from the vulva. "The other response was observed in the patient with KIT-mutated vulvar melanoma lacking a BRAF mutation." (PMID 28428884, 2017).
Adamantinomatous Craniopharyngioma (3 papers, 2016 to 2025). A craniopharyngioma consisting of broad strands, cords and bridges of a multistratified squamous epithelium with peripheral palisading of nuclei. "While BRAF mutations represent a target for papillary tumors, adamantinomatous craniopharyngiomas currently lack such a target." (PMID 41310495, 2025). "Herein, we examined the expression and localization of β-catenin, BRAF p.V600E (V600E), and triggering receptor expressed on myeloid cells-1 (TREM-1) in 58 samples including 20 pCPs, 26 adamantinomatous craniopharyngiomas (aCP), and 12 RCCs." (PMID 27409178, 2016).
astrocytic tumor (3 papers, 2013 to 2024). A glial tumor of the brain or spinal cord showing astrocytic differentiation. "PA is a low-grade astrocytic tumor (CNS WHO grade 1) characterized by MAPK pathway alterations (typically, KIAA1549::BRAF gene fusion)." (PMID 38544524, 2024). "IHC detection of BRAF V600E mutant protein is an accurate and reliable alternative method that may be diagnostically useful when dealing with morphologically challenging pleomorphic astrocytic tumors in which the differential diagnoses include PXA and GBM/giant cell GBM." (PMID 24252190, 2013). "Therefore, BRAF V600E mutation assessment may be a potentially useful marker in the differential diagnosis of GBM/giant cell GBM vs. “PXA with anaplastic features” and in identifying BRAF V600E mutant astrocytic tumors suitable for targeted therapy." (PMID 24252190, 2013).
atopic dermatitis (3 papers, 2016 to 2025). "Dry skin is indeed listed as one of the side effects–interestingly, the association between this phenotype and the drug is mediated by the proteins coded for by genes RAF1 and BRAF, both of which have been linked with atopic dermatitis in previous work." (PMID 39911831, 2024). "Here, we systematically test the effect of compound BRAF/RAF1 ablation in epidermis and show that it gives rise to a progressive disease strongly resembling human atopic dermatitis." (PMID 27431613, 2016). "Mice lacking BRAF/RAF1 in keratinocytes develop a disease clinically very similar to human atopic dermatitis." (PMID 27431613, 2016).
autism (3 papers, 2018 to 2025). Persistent deficits in social interaction and communication and interaction as well as a markedly restricted repertoire of activity and interest as well as repetitive patterns of behavior. "In the Simons Foundation Autism Research Initiative (SFARI) database, three genes (BRAF, GRIN2A, MTOR) are identified as strong autism risk genes." (PMID 35883654, 2022).
bladder tumor (3 papers, 2020 to 2025). "In veterinary science, this method was recently shown for the first time in a study of canine bladder tumours to detect the BRAF p.V595E mutation through commercial AI histology software (Visiopharm 2022.11, Hørsholm, Denmark)." (PMID 38787171, 2024). "Conversely, after 2 months of anti-BRAF/MEK therapy, macroscopic hematuria ensued, only to further reveal an apparently “de novo” bladder tumor, ~2.8 cm in diameter, localized on the right lateral wall." (PMID 40002790, 2025).
brainstem glioma (3 papers, 2016 to 2022). "A genomic profiling study of nine adult brainstem gliomas identified one BRAF V600E mutation and two PIK3CA mutations." (PMID 27556016, 2016). "For example, adults with recurrent brainstem glioma harboring a BRAF V600E mutation may qualify for the recently initiated NCI-MATCH study, which includes an arm for patients with tumors with BRAF V600E mutation to receive a combination of dabrafenib and trametinib." (PMID 27556016, 2016).
Burkitt lymphoma (3 papers, 2016 to 2018). A rare form of malignant mature B-cell non-Hodgkin lymphoma. "Herein, we describe a case of BRAF-mutation positive ECD in a patient with Burkitt lymphoma, and we review recent literature." (PMID 30474563, 2018). "Herein we describe a case of BRAF-mutation positive ECD in a 48 year old male who was diagnosed with ECD after experiencing increasing weakness and failure to thrive after completing treatment for Burkitt lymphoma." (PMID 30474563, 2018).
cerebellar tumors (3 papers, 2019 to 2025). "A tandem duplication at 7q34 resulting in a fusion gene between BRAF and KIAA1549 is the most common genetic alteration occurring in 60–70% of pediatric PAs, mainly in tumors of the cerebellum, brainstem and optic pathway; however, its reliable detection is technically challenging." (PMID 31362435, 2019).
chordoma (3 papers, 2011 to 2021). Chordomas are rare malignant tumors arising from embryonic remnants of the notochord in axial skeleton. "Our negativeKRAS/BRAF results are similar to the negativefindings of another study which tested chordomas for KRAS andBRAF mutations and their relationship with theFGFR-RAS/RAF/MEK/ERK-ETS2/brachyury pathway." (PMID 21602918, 2011). "Also, several oncogenes such as BCL2 (11.5-fold), BRAF (9.8-fold), KRAS (4.9-fold), and SRC (2.8-fold) are significantly stronger expressed in the recurrent chordoma cell line." (PMID 34330313, 2021). "Of these, 27 compounds selectively targeted chordoma cells but not human dermal fibroblasts, and 21 of these 27 compounds (78%) represented EGFR/ERBB family inhibitors, of which five also represented BRAF inhibitors." (PMID 27102572, 2016).
colon adenoma (3 papers, 2011 to 2023). An adenoma that arises from the colon. "We also aimed to determine whether KRAS, BRAF mutations, and/or MLH1 hypermethylation is associated with Fn infection in colon adenomas." (PMID 37772997, 2023). "However, it is likewise reasonable that genetic heterogeneity defines colon adenomas and that KRAS and BRAF mutations are subclonal." (PMID 30166531, 2018).
cystadenoma (3 papers, 2012 to 2022). A benign or borderline cystic epithelial neoplasm arising from the glandular epithelium. "It has also been reported that a small proportion of these cystadenomas become clonal and that KRAS or BRAF mutations in some of these clonal cystadenomas lead to the development of SBTs, which are the precursors of LGSOCs." (PMID 35326657, 2022).
developmental delay (3 papers, 2007 to 2019). "In addition to somatic mutations, germline mutations in BRAF have recently been identified as causing CFC syndrome, a multiple congenital anomaly disorder whereby individuals have characteristic craniofacial dysmorphisms, cardiac defects, ectodermal anomalies and developmental delay." (PMID 18060073, 2007).
dilated cardiomyopathy (3 papers, 2020 to 2023). Cardiomyopathy which is characterized by dilation and contractile dysfunction of the left and right ventricles. "ARAF, BRAF and RAF1 transcripts were readily detected in human hearts, but only BRAF transcript expression was significantly increased in dilated cardiomyopathy samples; ARAF and RAF1 transcripts showed decreased expression." (PMID 35147166, 2022).
embryonal tumors (3 papers, 2023). "We were able to define five groups of patients: diffuse gliomas with H3K27M mutation (18 patients), diffuse gliomas without H3K27M mutation (10 patients), circumscribed benign focal gliomas with BRAF alterations (9 patients), and embryonal tumors (3 patients)." (PMID 37936887, 2023).
gallbladder cancer (3 papers, 2020 to 2022). "The experience of the combined inhibition of BRAF and EGFR is limited to a single case report, which demonstrated a complete response of heavily pretreated BRAF-mutated gallbladder cancer to vemurafenib, dabrafenib and irinotecan." (PMID 34681592, 2021). "A small subset of gallbladder cancers is characterized by the presence of BRAF codon 600 substitutions." (PMID 34681592, 2021). "Therefore, additional study is needed to evaluate the effectiveness of established anti-cancer agents targeting tyrosine kinase and BRAF in gallbladder carcinomas." (PMID 32460791, 2020). "Therefore, when considering the relationship between FAM83H/ZNF16 and tyrosine kinase- and BRAF-pathways, the inhibitors of the tyrosine kinase receptor and BRAF might be useful for the treatment of the poor prognostic subgroup of gallbladder carcinoma with high expression of FAM83H/ZNF16." (PMID 32460791, 2020).